IFNB1 (interferon beta 1)
Diseases named in the same sentence as IFNB1 in open-access papers (continued):
Sharing a sentence is not in itself a finding about the gene and the disease.
infection (2,098 papers, 1988 to 2026). The state of being infected such as from the introduction of a foreign agent such as serum, vaccine, antigenic substance or organism. "Moreover, we observed that wild-type TBK1, but not its mutants Y591F and Y591E, increased levels of phosphorylated IRF3 and Ifnb1 production induced by HSV1-GFP infection when PTK2B was co-expressed in TBK1-deficient MEF cells." (PMID 37989995, 2023). "In contrast, only an HRV-16 pre-infection with a MOIs of 0.5 boosted IFNB1 expression by AECs infected with the Delta variant, and we did not observe an increase in IFNB1 expression by AECs infected with the Omicron variant when pre-infected with any HRV-16 infectious dose." (PMID 35484173, 2022). "As reported, we found the level of Ifnb1 mRNA (encoding IFN‐β) was significantly elevated upon infection with Sendai virus (SeV) or simulation with 5′‐pppRNA in siMETTL14 transfected peritoneal macrophages compared to that in control siRNA (siCtrl) transfected cells." (PMID 34047074, 2021). "Compared with the control, P. zengyii pretreatment significantly increased the mRNA expression of IFNB1 at 12 h post‐infection (hpi) and the secretion of IFN‐β at 24 and 48 hpi." (PMID 40600055, 2025). "PBEC were able to be infected with IAV and infection caused an increase in expression of immune genes including CXCL10, IFNB1, ISG15 and SOCS1." (PMID 40496017, 2025). "IFNB1 mRNA expression in A549 and Hep2 cells induced by 3 or 6 h of stimulation with poly(I:C) or infection with SeV was increased by treatment with P. zengyii." (PMID 40600055, 2025). "The induction levels of antiviral genes—including DDX58, OAS1, OAS2, ISG15, MX2, IFI44L, RTP4, and IFNB1—were markedly reduced in KO cells compared to WT cells post-infection." (PMID 40872812, 2025). "Collectively, these results indicate that both TLR4 and SLAMF1 are required for the early induction of TNF mRNA by HMPV in human MDMs, while only SLAMF1 contributes to HMPV-mediated IFNB1 expression at later stages of infection." (PMID 41346628, 2025). "Surprisingly, the expression of IFNB1 mRNA was significantly upregulated at 6 h post-infection (hpi) and 12 hpi following preincubation with P. zengyii." (PMID 40331950, 2025). "TLR4 deficiency markedly reduced the early (3 h post-infection) HMPV-induced TNF mRNA expression, whereas HMPV-stimulated IFNB1 mRNA expression was unaffected." (PMID 41346628, 2025). "Compound 10 treatment elevated the expression of cellular antiviral genes, including Ifnb1, Isg15, Isg56, and Mx1, at 4 days post-infection (dpi)." (PMID 40298378, 2025). "TLR4 overexpression significantly increased HMPV-stimulated TNF and IFNB1 mRNA levels at later stages of infection." (PMID 41346628, 2025). "NF-kB binds to specific elements within the IFNB1 promoter, acting as a key mediator in its activation and ensuring an effective production of this cytokine under conditions of cellular stress or infection." (PMID 40507959, 2025). "RT-qPCR analysis of RNA isolated from hGBOs at 48 h post-infection revealed a robust upregulation of IFNB1 and IFNB1-stimulated IFIT1, MX1, CXCL10, and OAS1." (PMID 41255708, 2025). "In nasal epithelial cells, IFNB1 expression remained 50-fold upregulated from 48 h post-infection (hpi)." (PMID 40142465, 2025). "Infection of macrophages for 24 h at 34°C with ts SeV-Cas9 induced less IFNB1 and IFIT1 expression compared to WT SeV-Cas9, which is in agreement with our findings in 293T cells." (PMID 39494910, 2024). "Strong induction of IFNB1, comparable to the A549 cell line, was observed in most cell lines after infection with VSV, while treatment with pan-IFN had only minor effects." (PMID 38743751, 2024). "Treatment with these inhibitors reduced IFNB1 expression in A549 and HeLa cells following infection, with the PERK inhibitor exhibiting a greater effect." (PMID 39100663, 2024).
infection (continued). "Infection of wild type (WT) A549 cells with Sendai virus (SeV) or Zika virus (ZIKV) resulted in robust IFN-I (IFNB1) and IFN-III (IFNL1) transcription and activation of both IRF3-dependent (ISG54) and NF-κB-dependent (NFKBIA) genes." (PMID 38001254, 2024). "For necessity, Ao infection of a naive T. gondii strain (ME49) will promote IFNB1 expression relative to an uninfected control." (PMID 38817668, 2024). "THP1 monocytes with CRISPR-mediated knockout of either STING or cGAS accumulated fewer IFNB1 transcripts compared to wild-type cells following infection with HCMV AD169." (PMID 38932169, 2024). "Second, we knocked down Ptk2b in mouse macrophages RAW 264.7 cells and found that Ptk2b knockdown significantly impaired mRNA levels of Ifnb1, Ifit1 and Cxcl10 induced by infection with HSV1-GFP." (PMID 37989995, 2023). "We assessed IFIT1 and IFNB1 expression in HeLa cells in response to 5xSunTag-EMCV(LZn) infection using smFISH—a sensitive, single-cell method for analysis of gene expression." (PMID 37814072, 2023). "qPCR assays showed that Ptk2b deficiency significantly attenuated the mRNA levels of Ifnb1, Ifit1 and Cxcl10 stimulated by HSV1-GFP and VSVΔM51-GFP infection." (PMID 37989995, 2023). "MVA∆E5R infection of BMDCs potently upregulated Ifnb1, Ifna, Ccl4, and Ccl5 gene expression, whereas MVA infection had modest induction." (PMID 37217469, 2023). "It is has been shown that IFNB1 induction is significantly weaker in SCOV2 infection, with its induction in the H1N1 case occurring earlier in the infection progress and higher peaks being strongly correlated with infectious titers." (PMID 38077337, 2023). "Comparing the fold inductions of the analyzed transcripts reflects that the transactivation of Ifnb1 is among the strongest responses at this early time point after infection." (PMID 37289084, 2023). "qPCR results showed that Ptk2b deficiency dramatically reduced mRNA levels of Ifnb1, Ifit1 and Cxcl10 stimulated by HSV1-GFP or VSVΔM51-GFP infection." (PMID 37989995, 2023). "PTK2B ASOs treatment downregulated levels of PTK2B protein, and reduced the levels of IFNB1 mRNA induced by the infection with HSV1-GFP or VSV-GFP." (PMID 37989995, 2023). "qPCR results indicated that PTK2B overexpression significantly enhanced the mRNA levels of Ifnb1, Ifit1 and Cxcl10 induced by infection with HSV1-GFP or VSVΔM51-GFP in MEFs." (PMID 37989995, 2023). "For example, infections with different viruses result in IFNB1 expression in <1%–30% of infected cells." (PMID 37814072, 2023). "We first established that (CC001xCC071)F1 MEFs responded to infection with as rapid induction of Ifnb1 expression as CC001 MEFs, suggesting that this CC071 trait was recessively inherited." (PMID 37733807, 2023). "In contrast, microglia derived from Mavs-/- mice displayed an abrogated response to infection, with minimal changes in gene expression in most genes in the array and a greater than 4,000-fold reduction in Ifnb1 expression versus WT infected microglia." (PMID 35584192, 2022). "The pro-inflammatory cytokine Il-6 and antiviral type I interferon Ifnb1 were significantly up-regulated in the lung as early as 1-day post-infection, and gradually declined afterwards." (PMID 35503798, 2022). "Yet, when comparing the infection regimens with each other, we found that Ifnb1 overexpression was comparable between both infection groups (p = 0.93)." (PMID 36365071, 2022). "In WT lung epithelial cells, infection with VACV∆C7L induced higher expression levels of Ifnb1, Ccl4, and Ccl5 compared with WT VACV." (PMID 35351885, 2022). "We found that IFNB1 was up-regulated at day 4 post-infection, the timepoint when IFN-activated immune cells were highest." (PMID 35271298, 2022). "Next, we revealed that at the early time point after infection (2 h.p.i.), robust induction of the cytokines, including Ifnb1, Tnfa, Il12b, and inflammasome genes Nlrp3 was obtained, which is consistent with a previous study." (PMID 35604097, 2022).
infection (continued). "At 96 h following infection we assessed correlations between relative expression of IFNB1 and IFNL2 in individual primary bronchial epithelial cell lines and viral replication (SARS-CoV-2 copy number) in those cultures." (PMID 35484173, 2022). "The expression levels of Ifnb1 in the lung, liver, and spleen of Prmt9CKO mice were significantly higher than those of Prmt9WT mice organs after infection with VSV." (PMID 36028484, 2022). "After infection, Ifnb1 and Ddx58 expression was significantly enhanced in Lect2-TG mice, whereas their expression was impaired in Lect2-KO mice." (PMID 35676290, 2022). "When examining cytokine responses in the lungs after infection, we found that treatment with H-151 considerably decreased the expression of Ifnb1 and ISGs (for example, Gbp2, Irf5 and Irf8) at 6 dpi32,35." (PMID 35045565, 2022). "Infection with SARS-CoV-2 strongly induced the expression of type I (IFNB1) and type III (IFNL1) IFNs as well as several ISGs, although peak expression levels resulting from SARS-CoV-2 infection were lower than after H1N1 infection." (PMID 35840680, 2022). "The results indicated that infection of ASFVΔI267L induced markedly higher mRNA levels of IFNB1 gene than wild-type ASFV in PAMs." (PMID 35089988, 2022). "We observed that IFNB1 and IFNL2 expression were significantly greater following HRV-16 than following infection with SARS-CoV-2 WA-01, SARS-CoV-2 Delta variant, or SARS-CoV-2 Omicron variant at equivalent MOIs." (PMID 35484173, 2022). "The results further showed that the Ifnb1 mRNA level was increased in Prmt9CKO macrophages after infection with VSV, whereas VSV mRNA, VSV titers and VSV protein were significantly decreased in Prmt9CKO macrophages." (PMID 36028484, 2022). "The results showed that the deficiency of Cgas markedly reduced the Ifnb1 transcripts in the liver and IFNβ in the blood at both time points post infection, indicating that cGAS is important for the induction of IFNβ during S. japonicum infection." (PMID 35108342, 2022). "As compared to uninfected cultures, the relative increase in expression of IFNB1 following infection with HRV-16 was significantly greater than following infection with SARS-CoV-2 WA-01 (median increase expression 4.4-fold vs. 1.4-fold, p < 0.0001)." (PMID 35484173, 2022). "Yap+/- mice showed increased Ifnb1 and Irf3 expression in both mRNA and protein levels upon infection, which is in support of our in vitro results." (PMID 35503798, 2022). "In the present study, both IFN-ALPHAOMEGA and IFNB1 were extremely significantly up-regulated (LFCs >5) at three timepoints after YC-2020 infection, which has been detected in some previous RNA-Seqs toward PRRSV-2 infection." (PMID 36338035, 2022). "Consistently, overexpression of miR-543 significantly increased the Ifnb1, Ifna4, and Cxcl10 mRNA levels after infection with SeV, VSV or stimulation with 5’PPP-RNA compared with the NC group in macrophages." (PMID 36028484, 2022). "IFNB1 expression was also elevated following infection; however, IFNL1, IFNL2, and IFNL3 expression clearly dominated the innate immune response." (PMID 36268025, 2022). "Upon VACV∆C7L infection, lung AECIIs induce the expression of Ifnb1 and IFN-stimulated genes (ISGs) via the MDA5 and STING-dependent cytosolic DNA and dsRNA-sensing pathways." (PMID 35351885, 2022). "A study demonstrated that infection of human DCs with PRVABC59, P6-740, MR-766, and Dakar 41524 strains resulted in the induction of notable IFNB1 gene transcription but caused inhibition of type I IFN protein translation." (PMID 35371036, 2022). "The critical observation is that in SARS-CoV-2 infected A549-WTACE2 cells that induced IFNB1 and displayed abundant and dispersed IFNB1 mRNA by 48 h post-infection, 72% retained the majority (>50%) of IFNB1 mRNAs in the nucleus." (PMID 34315815, 2021).
infection (continued). "We observed a significant reduction in the I-IFN Ifnα4 and Ifnb1 mRNAs in HSV-1-infected primary microglia with linc-AhRA overexpression at different times post-infection." (PMID 34646390, 2021). "The expression of Ifnb1, Il6, and Ifna4 were increased in BMDMs from Mettl14+/− mice after infection with SeV or treatment with 5′‐pppRNA, compared to that in wild‐type BMDMs from Mettl14+/+ littermates." (PMID 34047074, 2021). "We observed this effect at earlier times post-infection (24 or 36 h), though very few cells contain IFNB1 mRNA at or before these times." (PMID 34315815, 2021). "In PMH, quantification of Ifnb1, Ifnl2, and Ifnl3 transcript levels [murine Ifnl1 is a pseudogene] showed that infection elicited the expression of only Ifnb1, which was 40 times higher at 24 h than at 72 h p.i.." (PMID 34858876, 2021). "After infection, the IFNB1 locus is repositioned away from PCH, and this observation correlated with transcriptional activation of the promoter shortly thereafter." (PMID 32645843, 2020). "Consistently, the relative expression of Ifna2, Ifna4 and Ifnb1 was highly decreased in the spleen and LN 16 h post-infection in CD169-Cre+/ki x Usp18fl/fl mice." (PMID 32210083, 2020). "Traf3ip3fl/flLyz2-Cre+ mice had increased serum IFN-β at 8 h post-infection, as well as increased Ifnb1 mRNA expression in lung, liver and spleen 24-h post-infection." (PMID 32366851, 2020). "The expression of IFNB1 is, at least in murine cells, tightly regulated by different forms of NF-κB dimers in the initial response to infection, as reviewed by Balachandran and Beg." (PMID 32645843, 2020). "We observed that the expression of Ifnb1 after stimulation with poly(I:C) or 5′-pppRNA or infection with SeV was significantly lower in Trim35−/− macrophages than in Trim35+/+ macrophages." (PMID 32562145, 2020). "Conversely, expression of IE1dl410-420 led to a marked increase in infection-related induction of the IFNB1, IFNL1, CCL5, TNF and PML genes." (PMID 32365141, 2020). "Although WT cells efficiently expressed the IFNB1 gene upon infection by PR8-delNS1 and SeV, its induction in RIG-I KO cells was undetectable." (PMID 32677963, 2020). "The defect in Tmem173 suppression in the Mirn23a-/- macrophages, more evident over time, correlated with greatly increased Ifnb1 induction by 24h post-infection, consistent with increased STING activity." (PMID 33108406, 2020). "Two other studies both used MeRIP-seq to establish the presence of m6A in IFNB1 induced through dsDNA treatment or by infection with the dsDNA virus HCMV73,74." (PMID 32313079, 2020). "Host genes commonly upregulated upon infection with either Ot strain include IFNB1 (interferon beta) and genes involved in regulating the type-I interferon response: IRF9 (interferon-regulated factor 9) and STAT1/2." (PMID 32620750, 2020). "We observed a significant increased level of mRNA expression of Ifnb1 and Ifnar1 in the lung and spleen tissue at both 21 and 84 days after infection in comparison with uninfected PBS control mice." (PMID 31801478, 2019). "To this end, we infected mice intratracheally with P. aeruginosa PA14, and compared the course of infection between WT and IFN-deficient (Ifnar1−/− and Ifnb1−/−) animals." (PMID 31572395, 2019). "The mRNA levels of Ifnb1 and Tnfa were decreased in Ubxn3b−/− cells at 6 h after infection, which was accompanied by increased viral load." (PMID 29899553, 2018). "We show here that ZFR is the linchpin of a mechanism that controls RNA processing and decay to strongly affect the magnitude of IFNB1 transcriptional induction in response to infection." (PMID 29559679, 2018). "IL6, IFNB1, CXCL10, and CCL5 gene expression was significantly elevated in ATII cells following infection and was reduced by the addition of apocynin (except for IFNB1)." (PMID 30341336, 2018). "Measurements of IFNB1 transcript by qPCR normalized to the housekeeping gene L32 in A549 cells at 10 hr post infection at an MOI of 0.5." (PMID 29451492, 2018).
infection (continued). "qPCR analysis indicated that transcription of downstream genes including Ifnb1, Cxcl10, and Il6 following infection with HSV-1 and VACV was markedly inhibited in Zcchc3−/− mouse bone marrow-derived macrophages (BMDMs) and dendrite cells (BMDCs)." (PMID 30135424, 2018). "L2 transcription continues to be detected even at 72 h post-infection when IFNB1 has become repressed by post-induction repression mechanisms, implicating a potentially novel enhancer inactivation and decommissioning mechanism." (PMID 30352805, 2018). "In this study, the associated genes (IFIH1, IFNB1, DDX58, CXCL10 and IL12A) in the RIG-I-like receptor signaling pathway were increased obviously at 8 h post-infection(p<0.05), compared to 3 h post-infection." (PMID 28938587, 2017). "A separate study showed that macrophage Ifnb1 expression upon infection with the M. tuberculosis clinical isolate 1254 was equivalent between wild-type cells and macrophages deficient in Tlr4, Tlr2, Tirap, Myd88, or Trif." (PMID 29230217, 2017). "RIG-I agonist treatment induced modestly higher, but overall similar levels of IFNB1 transcription as compared to during ZIKV PR-2015 infection." (PMID 28152048, 2017). "When we assessed IFNB1 gene induction over an infection time-course, up-regulation of transcription occurred as early as 12hpi and remained at or near peak levels through 72hpi." (PMID 28152048, 2017). "We assayed SAMHD1 expression in several relevant cell types in vitro, in response to interferon beta (IFNB1) treatment or infection." (PMID 26936683, 2016). "To compare the impact of MyD88 on host and viral gene expression directly, we measured the expression kinetics of Tnf, Il6 and Ifnb1 with the viral Ie1 gene in the context of the infection of Myd88-/- and WT BMDMs." (PMID 25856589, 2015). "On day 4 post-infection, enhanced expression of Ifnb1 correlated with a 11-fold increase in Setdb2 transcript when normalized to uninfected lungs (11.0 ± 1.38 vs. 1.0 ± 0.43; p<0.001)." (PMID 26709698, 2015). "120G8 mAb injection dramatically reduced circulating IFN-I titers and splenic Ifnb1 expression at d1.5 after infection." (PMID 25954804, 2015). "In contrast, infection with EMCVΔL lacking both L protein and EMCV L region RNA induced lower levels of Ifnb1 or Ifit1 than infection with EMCV ZnC19AC22A at two different multiplicities of infection (MOI)." (PMID 24550253, 2014). "As detected by qRT-PCR, increased levels of IFNB1 transcripts upon infection correlates with induction of IFN-stimulated signaling registered in the microarray analysis." (PMID 25015256, 2014). "To analyse and compare kinetics of Ifnb1 induction after intragastric infection challenge with Lmo-InlA-mur-lux and Lmo-EGD-lux we developed a dual luciferase detection model." (PMID 23617550, 2013). "6, 12 and 24 hours after infection, mRNA levels of Ifnb1, Tnf and Ifng were assessed in whole lung homogenates by Q-PCR, demonstrating an early upregulation of Ifnb1 as soon as 6 hours after infection, which continued to rise at later time points." (PMID 24244159, 2013). "This is in contrast to the LRRFIP1-dependent phosphorylation of CTNNB1 at Ser552 upon infection with Listeria monocytogenes, which promotes its transcriptional activation required for IFNB1 production in mouse macrophages." (PMID 23785285, 2013). "Up-regulation of type I and III IFNs was clearly seen during the early phase of infection by a strong increase in the expression of Ifnb1, a moderate augmentation of Il28b (IFN λ) and a slight but distinct accession in several Ifna genes." (PMID 22815957, 2012). "These ISGs included Ifna2, Ifna4, and Ifnb1, which were induced to high levels in all four strains at 12 hours (>1000-fold) and 24 hours (>100-fold) post-infection, and likely represent early IRF3-mediated gene expression." (PMID 21379341, 2011).